EGFR (epidermal growth factor receptor)
Diseases named in the same sentence as EGFR in open-access papers (continued):
Sharing a sentence is not in itself a finding about the gene and the disease.
tumor (continued). "We found that Met was not expressed in any of these tumours, suggesting that Met was not involved in the resistance of MGG70RR-GSC to EGFR inhibitors." (PMID 30644426, 2019). "The assessment of CTCs to determine EGFR mutation status, ALK rearrangements and PD-L1 status lends itself to the identification of patients for targeted therapies, be they oncogenic or immune-related, in patients where tumour biopsy tissue may not be available." (PMID 30889898, 2019). "These tumours also on the protein level typically showed no or low expression of KRT5 and KRT14, aberrant expression of KRT20 and a low expression of EGFR, but a high expression of ERBB2." (PMID 30258198, 2018). "Of note, for one child with EGFR-ITD-positive mixed cellularity CMN (PD37214), both primary tumor and recurrence were studied, with no additional driver events apparent at relapse." (PMID 29915264, 2018). "EGFR, HER3 and HER4 gene status was assessed in 60 non-overlapping nuclei from the invasive part of the tumor." (PMID 30521571, 2018). "EGFR and PTEN were used as positive and negative controls respectively, and ERBB4 copy number is similar to the known tumor suppressor PTEN." (PMID 29342193, 2018). "This α-EGFR-LIGHT fusion protein was shown to be able to overcome resistance to anti-PD-1 and convert non-T cell infiltrating (“cold”) tumor to tumors with increased infiltrating T cells (“hot”) tumor." (PMID 30577797, 2018). "Taken together, our phylogenetic analysis suggests that GBM subclones with amplification of EGFR and MDM4 were eliminated by surgery and RT/TMZ treatment, while a population of tumor cells without the amplification remained viable." (PMID 29416795, 2018). "In conclusion, it is shown here that LPS have no impact on the clonogenicity of tumor cells, but induce a radioresistance in TLR-4 and EGFR expressing NSCLC cells." (PMID 29989005, 2018). "None of the MDL tumours expressed basal markers [cytokeratin (CK) 5/6; CK14; and epidermal growth factor receptor]." (PMID 29344954, 2018). "In contrast, the bivalent [64Cu]Cu-α-EGFR-EGFR-NODAGA TM has not reached its maximum concentration 1.5 h p.i. and can further enrich at the tumor site during the following 22.5 h (red bars)." (PMID 29876011, 2018). "We found significantly higher EGFR expression in the UMSCC-104 cell line, which originated from an HPV-positive tumor that did not respond to treatment, than in UMSCC-1 cells." (PMID 30100997, 2018). "We observed that irradiation resulted in EGFR activating PERK, which induced eIF2α phosphorylation and ER chaperone protein GRP94 to regulate the radioresistance of tumor cells, but did not affect CHOP, which is downstream of PERK." (PMID 30414263, 2018). "The EGFR-, HER3-, and non-targeted molecules induced almost complete tumor remission, whereas only partial tumor regression and fast regrowth were found for scFv323/A3hu3-Fc-scTRAIL." (PMID 29541416, 2018). "In this study, we found by multivariate Cox’s regression analysis that both low EGFR and low HIF-1α mRNA levels are independent negative prognostic markers for tumor-specific survival in analyzed STS patients." (PMID 30513863, 2018). "Stimulation of the DK-MGhigh or primary tumor cells with EGF did not result in elevated phosphorylation of the mutant receptor, despite the marked increase in phosphorylation of the wild-type EGFR, which is in contrast to previous reports." (PMID 29492217, 2018). "We did not detect gene amplifications in EGFR (n = 8) or Her2 (n = 16) by FISH and CISH, respectively; MYCN amplification was seen in one tumor using NGS." (PMID 29869738, 2018). "The two cases who showed the primary tumours with KRAS wild type and the corresponding ovarian metastasis with KRAS G12S or G12V did not received any anti-EGFR antibody before oophorectomies." (PMID 29662660, 2018).
tumor (continued). "Resection of the main tumor conferred a better outcome in patients without EGFR mutation or with unknown EGFR mutation status and had not been treated with EGFR-TKI therapy (P = 0.003), but not in those with activating EGFR mutation and had been treated with EGFR-TKI (P = 0.857)." (PMID 29435191, 2018). "Among all the markers we analyzed, the expression of EGFR in CGBC 01 was the most interesting, as it was not present on the original tumor by IHC." (PMID 29484537, 2018). "Our data suggest that downregulation of ALIX provides a mechanism for enhancing both EGFR activity and PD-L1-mediated evasion of anti-tumor immunity in BLBC, driving cell-autonomous and non-cell-autonomous mechanisms of tumor survival." (PMID 30021161, 2018). "This setting mimics the complex and functional environment of metastases including tumor stroma and tumor microenvironment and serves as ideal model for evaluation of the feasibility of the NIS gene therapy concept after EGFR-targeted nonviral gene transfer." (PMID 29190908, 2017). "Interestingly, first-line sensitivity to EGFR TKIs in NSCLC has been associated with pre-existent Akt activation that is suppressed by EGFR inhibition, while treatment with EGFR TKIs failed to block Akt signaling in tumor cells intrinsically resistant to these drugs." (PMID 28871105, 2017). "For activation of STAT3 both EGFR mediated signaling as well as IL-6 signaling has been shown to be relevant and in NSCLC tumor cells JAK1 and not JAK2 was determined as the signal relaying kinase." (PMID 28402937, 2017). "In contrast, EGFR signaling is affected by neither EGFR inhibitors nor rEGF in mesenchymal-like ESCC cells, and thereby squamous cell differentiation and tumor cell growth inhibition do not occur in mesenchymal-like ESCC cells treated with EGFR inhibitors." (PMID 28764725, 2017). "Unfortunately, the influence of EGFR mutant NSCLC tumor cells imposed on the bone niches was not clear in this study, as the HCC827 NSCLC cell line (EGFR mutant cell line) bone metastatic model was not established." (PMID 29113396, 2017). "Moreover, growth factor receptors, such as Epidermal growth factor receptor (EGFR) and hepatocyte growth factor receptor (HGFR, c-Met), may activate Src, which triggers phosphorylation and endocytosis of E-cadherin, leading to dissemination of tumor cells from the tumor mass." (PMID 29112161, 2017). "Unlike the EGFR-driven xenograft study in H1975, partial inhibition of H1975-HGF tumor growth was observed with c-Met-LF monovalent antibody or the IgG2σ version of JNJ-61186372." (PMID 27786612, 2017). "The HT-cetuximab combination affected neither the cell survival ability nor EGFR expression levels in CCD-18Co cells or in differentiated CaCo2 cells, indicating that its effect is specific for tumor cells." (PMID 29137335, 2017). "This tumor lacked HER2, EGFR, or CK5 and upon transplantation grew into a large mass within 2 weeks (data not shown)." (PMID 29164052, 2017). "Tumor samples derived from NSCLC patients can show robust activation of AKT, ERK, and STAT3 while EGFR is not activated." (PMID 29177004, 2017). "Moreover, the c-MET amplification locus could be detected in circulating tumor DNA, suggesting that the early initiation of c-MET inhibitors in those patients who respond to anti-EGFR therapies and do not display emergence of KRAS mutations in blood tests during anti-EGFR therapies." (PMID 28368335, 2017). "The study reported that EGFR-specific CAR observably potentiated cytotoxicity and induced secretion of IFN-γ and IL-2 in EGFR-positive cell lines and xenograft tumor models, but not in EGFR negative ones." (PMID 28356156, 2017). "The differential response of tumor lines HT29, Calu1, and LN229 to ENb-TRAIL is not sufficiently reflected by the levels of cell surface EGFR and DR5 alone." (PMID 28572590, 2017).
tumor (continued). "Randomized phase III clinical trials have shown a survival benefit of these anti-EGFR monoclonal antibodies in RAS wild-type metastatic CRC; however, tumor location has not traditionally been included as a stratification criterion in clinical trials." (PMID 29212173, 2017). "However, it is known that a percentage of KRAS or NRAS WT patients is not responsive to EGFR targeted therapy, leaving to hypothesize that additional mediators could be involved in the dysregulation of molecular mechanisms leading to tumor initiation and development." (PMID 29221448, 2017). "Furthermore, it is noteworthy that nuclear EGFR staining in tumor tissue sections has been reported with some, but not all, anti-EGFR antibodies, and in this situation it may be more difficult to verify the specificity of staining against EGFR-negative samples." (PMID 28646091, 2017). "The fraction of cases with 3+ expression differed significantly between PB-type and I-type tumours for HER3 (17% vs 51%, p<0.001), and for HER2 (0% vs 6%, p = 0.017), but not for EGFR." (PMID 27070783, 2016). "Other oncogenic pathways, such as EGFR and TGF-β, appear to be involved in tumor progression independent of MET signaling." (PMID 27013592, 2016). "Finally, whereas EGFR was proven to be involved in tumor tissue self-renewal and metastasis, no previously published biological or preclinical data could be identified to explain the propensity of EGFR-mutant NSCLC to develop BM and this remains to be explored." (PMID 27999344, 2016). "We next screened by flow cytometry this panel of cell tumour phenotypes with epithelial markers (EpCAM, E-cadherin, Muc1, claudin-3 andclaudin-4) or non-epithelial markers (N-cadherin, vimentin, CD66, EGFR, FGFR, EphB4,ALDH1 and CD49f)." (PMID 27711186, 2016). "For example, the analysis of expression of epithelial and mesenchymal markers in multiple NSCLC lines has revealed a negative correlation between the occurrence of tumor EMT and the cytotoxic response to EGFR inhibition in vitro and in xenografts." (PMID 27248176, 2016). "In cell lines derived from the same patient, EGFR and PODXL were expressed in the primary tumour cell line (SW480), but not in the metastatic derivative (SW620)." (PMID 27160084, 2016). "Among the 23 NSCLC patients with MET exon 14 skipping in our cohort, a 68 year-old non-smoker with MET, EGFR, and HER2 gene copy number gains in his tumor had relapsed." (PMID 27223439, 2016). "Taken together, these results suggest that EGFR wild-type, not EGFR mutant NSCLC with inherent resistance to EGFR inhibitors as opposed to acquired resistance, are more likely to show effective tumor inhibition using this combination treatment." (PMID 26962872, 2016). "While we failed to observe a consistent pattern of increased EGFR phosphorylation in KPH2 tumours, these tumours expressed higher levels of phosphorylated CaMKIIα." (PMID 26837714, 2016). "The expression of EGFR and HER3 was higher in tumours than in normal tissue, although this difference was not significant (data not shown)." (PMID 26844548, 2016). "The main objective of this study was to investigate the therapeutic targeting effect of cetuximab-IONPs against EGFR- and EGFRvIII-expressing GSCs in addition to GBM tumor non-stem cells." (PMID 25871395, 2015). "The interplay of signalling alterations and changes in metabolism and hypoxia in tumours following anti-VEGF and anti-EGFR treatment is not well understood." (PMID 26517691, 2015). "There were nine EGFR-TKI-refractory tumour lesions available, while there were no viable tumour cells in the primary lung tumour." (PMID 26400668, 2015). "Although EGFR inhibitor failed to retard SMG tumorigenesis in our model, we cannot completely rule out its involvement in tumor initiation." (PMID 26289340, 2015).
tumor (continued). "Some biomarkers are over-expressed on tumor surface not on normal cells, such as HER2, EpCAM, folate receptor, epidermal growth factor receptor (EGFR) and so on, which were usually used as the tumor targets." (PMID 25819426, 2015). "On the other hand, in settings when EGFR is ‘over‐expressed’ without genomic activation, or even less impressively merely ‘expressed’, similar to any of hundreds to thousands of other proteins in a tumor, EGFR may only be one of many wheels (downstream effectors) on the truck (cancer cell)." (PMID 25557400, 2015). "In humans, tumours are considered basal-like if they are negative for nuclear ERα, PR and HER2 (triple-negative) but positive for KRT5/6 or EGFR." (PMID 25633981, 2015). "Combination of non-competing antibodies targeting receptors, such as HER2, EGFR, and VEGFR3, can increase anti-tumor activity in preclinical models." (PMID 26225765, 2015). "The expression of tumour markers (Mucin1, EMMPRIN, EpCAM, EGFR) on TMV was low or absent, despite their presence on cells." (PMID 26626416, 2015). "Though the difference in the tumor size was not significant between the PDT and combination therapy groups, a difference in the expression of EGFR was observed between these two groups." (PMID 25918252, 2015). "This was observed to some extent with the ability of the MCF10CA1A EGFR-DEL cells injected into mice to temporarily colonize the brain and other sites after the primary tumour removal, though true metastases were not formed." (PMID 25969993, 2015). "HA binding to CD44 is involved in the stimulation of both receptor kinases (e.g., ErbB2, EGFR and TGFβ receptors) and non-receptor kinases (e.g., c-Src and ROK) required for a variety of tumor cell-specific functions leading to tumor progression." (PMID 24606718, 2014). "The last case was not amplified by FISH (EGFR/CEP7 = 1.13), possibly due to tumor heterogeneity given that the average copy number in the EGFR region by SNP array was 11.0." (PMID 24454681, 2014). "One reason for the rather minor effects of TKI on local tumour control could be that through heterodimerisation with other receptors of the EGFR-family, e.g. ErbB2, signaltransduction is still possible and therefore exclusively blocking the EGFR-TK is not sufficient." (PMID 25444177, 2014). "EGFR was overexpressed (≥1+) in 8 (42.1%) cases and HER-2 (3+) in 11 (57.9%) cases, regardless of tumour location or biological behaviour." (PMID 24454858, 2014). "We also identify a compact set of gene changes upon ErbB2 inhibition and demonstrate strong overlap with EGFR-driven cancers and further identify PHLDA1 as a novel negative feedback inhibitor and candidate tumor suppressor in ErbB2-dependent cancers." (PMID 25238247, 2014). "In the present study, L747S was identified in three patients who had never received EGFR-TKI therapy, indicating that the initial tumor contained resistant clones carrying L747S in varying proportions." (PMID 24396447, 2014). "ATC armed with anti-CD3 x anti-tumor associated antigen BiAbs exhibit high levels of specific cytotoxicity against tumor cells expressing Her2/neu, CD20, GD2, and EGFR via redirected non-MHC-restricted perforin/granzyme-dependent killing." (PMID 25008236, 2014). "The EGFR mutation L862R has to our knowledge not previously been described in the literature, but given its proximity to mutations known to be sensitive to EGFR-TKI (L858R and L861X), tumor clones bearing the L862R mutation could also be potentially responsive to EGFR-TKI." (PMID 24279718, 2013). "IHC staining was performed to detect EGFR, EGFRvIII and PTEN expression in all samples; however, one sample lacked pAKT staining due to an insufficient amount of tumor specimen." (PMID 23806066, 2013). "On the other hand, in the NALM6 tumor cell as a negative control, the [125I]PYK binding to EGFR-TK in tumor cell membranes was undetectable." (PMID 23494210, 2013).
tumor (continued). "Combined inhibition of EGFR and STAT3 by erlotinib and niclosamide more effectively induced apoptosis in tumor tissues without toxicity for normal tissues." (PMID 24019973, 2013). "In the present case, tumor cells showed marked cytoplasmic staining for GFAP and S-100 protein, whereas immunoreactivity for CK, EMA, chromogranin, EGFR and synaptophysin were all negative." (PMID 24137352, 2013). "Q-PCR displayed significantly reduced mRNA content in tumor tissue for COX-1 and EGFR (all transcripts), while COX-2 mRNA content was not significantly changed in tumor tissue compared to mucosa tissue." (PMID 24171795, 2013). "The key steps of each assay (antibody selection and labeling, reaction conditions and reagent concentrations) were optimized in preliminary experiments using tumor xenografts of cells expressing HER2 or/and EGFR (data not shown)." (PMID 22829865, 2012). "First, we compared TDLU involution characteristics in tumor subtypes defined by individual markers (ER, PR, CK5, and EGFR), dichotomously categorized as negative or positive, and adjusted for age and study site." (PMID 22513288, 2012). "Semi-quantitative reverse transcription-polymerase chain reaction (RT-PCR) and Western blotting were performed to detect expression of mRNA and protein, respectively, of RBM5, EGFR and KRAS in 120 paired non-tumor and tumor samples of NSCLC." (PMID 22537942, 2012). "The difference was apparent in the survival curves for patients with WT KRAS tumours who received anti-EGFR, those with WT KRAS tumours who did not receive an anti-EGFR agent and patients with MT KRAS tumours." (PMID 23174912, 2012). "EGFR knockdown, but not PAR34 treatment, decreased osteoclasts formed in vitro (p<0.01), reduced osteolytic lesion tumor volume (p<0.01), increased survivorship in vivo (p<0.001), and resulted in decreased MDA-231 growth in the fat pad (p<0.01)." (PMID 22276166, 2012). "Considering that the cell lines used for calibration overexpress EGFR and/or HER2, the number of these receptors per cell is unlikely to differ significantly between cultured cells and tumor xenografts." (PMID 22829865, 2012). "A phase II, placebo-controlled study of vandetanib (ZD6474), which targets VEGFR, EGFR and RET signaling, showed activity in patients with inoperable HCC but failed to meet its primary aim of tumor stabilization." (PMID 22470194, 2012). "Gene copy number gain was independent of tumour HPV status and present in 14% (19/140) of cases with no detectable impact on phosphorylated EGFR protein immunoexpression." (PMID 21407808, 2011). "Downregulation, but not enzymatic inhibition, of EGFR leads to reduced SLGT1 levels, reduced glucose uptake and autophagy of tumor cells." (PMID 21379385, 2011). "In our study EGFR expression in NSCLC was not significantly correlated with patients' age, gender, histopathologic type, cell differentiation, tumor size and TNM stages (P > 0.05)." (PMID 21385353, 2011). "Tumour xenografts from both ME180 (EGFR amplification) and Hela (EGFR wild type and without EGFR amplification) cell lines were established in a nu/nu mouse model." (PMID 21730982, 2011). "Despite the elevated frequency of EGFR-specific CTL in the circulation of HNSCC patients with high EGFR score, tumor growth was not inhibited." (PMID 21970318, 2011). "However, FGFR2 signaling in the tumor setting, where FGF2 and FGF7 are likely available from the surrounding microenvironment, may establish a paracrine pathway leading to continued cancer cell survival, growth and maintenance of transformation in the presence of EGFR targeted therapies." (PMID 21152424, 2010). "In the present study, EGFR overexpression was found in 50% of OSCC, while 97.8% of the tumor specimens were negative for Her-2." (PMID 20429940, 2010).